IL1B (interleukin 1 beta)
Diseases named in the same sentence as IL1B in open-access papers (continued):
Sharing a sentence is not in itself a finding about the gene and the disease.
tumor (continued). "In the tumor-free group, the host derived cytokines IL-1β, IFN-γ and TNF-α showed a time-dependent decline in concentration as a consequence of immune cell maturation while IL-17 levels remained stable in function of time." (PMID 24325392, 2013). "Our data revealed tumor-derived IL1β as one mediator of the pro-inflammatory response in MSCs exposed to tumor CM, which was found to be positively regulated by FAK and MAPK signaling and negatively regulated by TGFβ signaling." (PMID 24405819, 2013). "Further co-culture experiments between astrocytes and several lung cancer derived cell lines indicate that astrocytes secrete IL-6, TNF, and IL-1β, which stimulate tumor cell growth." (PMID 23596394, 2013). "Their tumour-promoting phenotype was induced by immune cell-secreted IL-1β and was dependent on NF-κB signalling." (PMID 24216702, 2013). "In their secreted form, IL-1α and IL-1β are involved in tumorigenesis and tumor invasiveness, whereas IL-1α, when expressed on the cell membrane, stimulates anti-tumor cell immunity." (PMID 24312101, 2013). "Further investigations into adipocyte-driven FABP4, HMOX-1 and IL-1β expression in tumor cells revealed that transcriptional upregulation of these factors in vitro correlates with increased protein levels." (PMID 24240026, 2013). "Nonetheless, IL-1β was reported to promote tumor cell growth and metastasis by inducing several pro-metastatic genes such as matrix metalloproteinases and endothelial adhesion molecules, as well as TGF-β, chemokines and growth factors." (PMID 24223129, 2013). "Immunosuppression induced by IL-1β usually acts in a dominant manner and masks the immunostimulatory anti-tumor effects of IL-1α." (PMID 23847618, 2013). "In cancer or chronic inflammation, MDSCs expand in the BM in response to diverse systemic pro-inflammatory cytokines, including IL-1β; they subsequently exit the BM as immature cells and seed at sites of tumor/inflammation." (PMID 23847618, 2013). "Due to the strong correlation between IL-1β and tumor progression, it is worthwhile to continue to explore Anakinra and other IL-1R antagonists as tumor immunotherapy options." (PMID 24273542, 2013). "In murine tumor models and in cancer patients, it was shown that IL-1β increases tumor invasiveness [reviewed in Ref." (PMID 23847618, 2013). "The secreted IL-1β induces inflammatory response and alters tumour microenvironment; however, it was also shown to enhance the growth and invasion abilities of cancer cells in an autocrine fashion." (PMID 23495140, 2013). "IL1β induces secretion of matrix metalloproteinases as well as angiogenic factors in the tumor microenvironment." (PMID 23762239, 2013). "Exosomal fibronectin was previously shown to induce IL-1β production by macrophages, thus contributing to create an inflammatory microenvironment that supports tumor growth." (PMID 24069378, 2013). "Mice challenged with Lewis lung carcinoma cells (LLC) transduced with human IL-1β exhibited increased tumor size and vasculature compared to LLC cells alone." (PMID 24273542, 2013). "The combination of IL-6 and its inducers TNF-α and IL-1β promotes tumor growth and survival in cancer patients through maintenance of chronic inflammation and induction of a tumor-supporting microenvironment." (PMID 23616009, 2013). "Interleukin-1β (IL-1β) is an important mediator of cancer-related inflammation and can be secreted by immune, stromal and tumor cells." (PMID 23174018, 2012). "IL-1β secretion into the tumour milieu also induces several angiogenic factors from tumour and stromal cells that promotes tumour growth through an increase of neovascularization in lung carcinoma growth in vivo." (PMID 23905066, 2012). "The inhibitory effect of tumour-derived IL-1β on tumour growth was further evaluated in immunocompetent wild-type mice." (PMID 23065753, 2012). "The mechanism through which IL1β contributes to tumor formation is at least partly through activation of HIF1α by IL1β." (PMID 23166763, 2012).
tumor (continued). "Taken together, these studies implicate IL-1β in promotion of tumor cell proliferation, migration, angiogenesis, invasion, and inhibition of immune surveillance." (PMID 23181220, 2012). "In tumour cells, AIM2 and RIG-I are required for IL-1β induction by EBV genomic DNA and EBV-encoded small RNAs, respectively, while NLRP3 responds to extracellular ATP and reactive oxygen species." (PMID 23065753, 2012). "Our data show that tumour-derived IL-1β can polarize TANs towards an N1 TAN-like immunostimulatory phenotype." (PMID 23065753, 2012). "Additional tumor samples need to be evaluated to investigate the value of IL-1β as a biomarker with clinical utility." (PMID 22296757, 2012). "Our data indicate that neutrophils are the mainly infiltrated cell type recruited by tumour-derived IL-1β." (PMID 23065753, 2012). "Based on this standard, it was found that one out of four mice bearing the control monolayer cells and six out of six mice bearing the IL-1β/TGF-β-induced neurosphere cells showed positive signals for tumor growth." (PMID 22330721, 2012). "Tumor-associated macrophages (TAMs) found in aggressive RCC tumors produce a variety of inflammatory cytokines, including interleukin-1β (IL-1β)." (PMID 23342250, 2012). "These factors include proinflammatory cytokines such as TNF-α, IL-1β, and IL-6 and factors produced by tumour cells, each of which can be derived from the tumour itself and also from the host tissues." (PMID 22629149, 2012). "We demonstrate that tumour-derived IL-1β can alarm the immune system to induce an influx of neutrophils to tumour sites." (PMID 23065753, 2012). "Using RNA interference, we next demonstrated that IL-1β-induced RCC tumor cell invasion required CEBPβ." (PMID 23342250, 2012). "We demonstrated that tumor-derived factor(s) stimulate macrophages to secrete a variety of soluble factors, including IL1β, a cytokine that we established was required for the crosstalk between tumor cells and macrophages." (PMID 23029025, 2012). "We report that IL-1β induced tumor cell invasion of RCC cells through a process that was dependent on the activity of matrix metalloproteinases (MMPs) and was independent of migration rate." (PMID 23342250, 2012). "We conclude from this study that the IL-1β/CEBPβ/MMP pathway is a major mediator of RCC tumor invasion and should be considered in the design of molecularly targeted therapeutics." (PMID 23342250, 2012). "More significantly, depletion of these neutrophils significantly blunts the antitumour effect of IL-1β, showing that IL-1β-induced TANs act as the effectors of tumour elimination." (PMID 23065753, 2012). "Activation of the inflammasome and production of IL-1β were identified as essential events for the optimal activation of anti-tumor T cells following treatment-induced ICD." (PMID 23112958, 2012). "We examined the effect of tumour-derived IL-1β on tumour growth in vivo by using HK1-IL-1β and HK1-vector cells." (PMID 23065753, 2012). "In summary, our results implicate the IL-1β/CEBPβ/MMP signaling pathway as a major mediator of RCC tumor cell invasion, and this pathway should be considered in the design of preclinical models of RCC to test its target-ability as an anti-metastatic therapy." (PMID 23342250, 2012). "The changes of Th17 cells along disease progression were accompanied by alterations of IL-1β, IL-6, IL-17A, IL-23 in serum and IL-1β, IL-6 in tumor tissues." (PMID 22994684, 2012). "We recently reported that tumor cell-derived factor(s) activated macrophages to produce IL1β, which in turn inactivated GSK3β, increased the levels of unphosphorylated β-catenin and stimulated Wnt signaling in HCT116 cells." (PMID 23029025, 2012). "Microenvironment-derived interleukin promotion of tumor growth has also been seen with IL-1β stimulation of melanoma and IL-6 promotion of primary colon cancer and liver cancers." (PMID 22277186, 2012).
tumor (continued). "Activation of MDSCs not only requires tumour-derived factors (e.g., tumour-derived prostaglandin E2 (PGE2)) but also IFN-γ produced by T cells and factors secreted by tumour stromal cells (like IL-1β, IL-4, IL-6, IL-10, IL-13)." (PMID 22778767, 2012). "We further studied the effect of tumour-derived IL-1β on tumour recurrence following surgical removal of the large primary tumours." (PMID 23065753, 2012). "We used TLR4 ligand LPS, TLR3 ligand polyI:C and the Jonuleit cytokine cocktail most commonly used in today’s DC-based tumor vaccines consisting of IL-1β, IL-6, TNF-α and PGE2 for the generation of immunogenic DC." (PMID 23185370, 2012). "The survival rates of mice carrying B16F10-IL-1β tumours (83.3%) were significantly better than for mice carrying tumours arising from B16F10-pro-IL-1β (25.0%, p = 0.003) or B16F10-vector (33.3%, p = 0.006) cells." (PMID 23065753, 2012). "Mechanistically, IL-1β-mediated anti-tumour effects depend on infiltrated immunostimulatory neutrophils." (PMID 23065753, 2012). "In conclusion, modulation of tumor growth and survival by IL-1β and IL-18 is complex and likely context-dependent." (PMID 23181220, 2012). "Together, these data indicate that depletion of TANs resulted in significant abrogation of the IL-1β-mediated antitumour activity, suggesting that TANs contribute to the antitumour activity of tumour-derived IL-1β." (PMID 23065753, 2012). "IL1β is a critical cytokine involved in inflammatory processes, including those within the tumor microenvironment." (PMID 23166763, 2012). "Macrophages and IL1β inactivate GSK3β in both HCT116 and Hke-3 cells and, consistently, stabilize Snail independently of the presence kRas mutations in tumor cells." (PMID 23029025, 2012). "Our study shows that IL-1β released from the tumor cells induces β1 integrins on the MCs and that axis mediates cell adhesion between the two cell types." (PMID 22296757, 2012). "We found that PDTC treatment significantly reduced the expression of TRAIL, IL-1β, TNFα, and MnSOD in the non-tumor bearing epidermis with a less appreciable decrease in tumors." (PMID 22761871, 2012). "In particular, the proinflammatory cytokine, interleukin-1β (IL-1β), has been shown to be important in promoting tumor angiogenesis." (PMID 23342250, 2012). "We next studied the functional significance of TANs in IL-1β-mediated tumour control by depleting the Ly6G+ cells in tumour-bearing animals." (PMID 23065753, 2012). "Collectively, the data show that high levels of tumour-derived IL-1β can inhibit tumour growth and local recurrence." (PMID 23065753, 2012). "In NPC, NLRP3, AIM2 and RIG-I inflammasomes were overexpressed in the tumour cells and were required for IL-1β production in response to PAMPs and DAMPs in the tumour microenvironment and therapeutic treatment." (PMID 23065753, 2012). "In the case of IL-1β, unbalanced levels of IL-1β, either too much (MDSCs preferentially expand) or too little (Tregs become prevalent), all lead to tumor progression." (PMID 22778760, 2012). "Collectively, these findings indicate that AIM2, RIG-I and NLRP3 inflammasomes in tumour cells are activated by factors from the viral and tumour microenvironments, thus contributing to IL-1β secretion." (PMID 23065753, 2012). "Mice with IL-1β-secreting B16F10-IL-1β tumours showed better survival (83.3%) than those with tumours arising from B16F10-pro-IL-1β (41.7%, p = 0.034) or B16F10-vector (33.3%, p = 0.01) cells." (PMID 23065753, 2012). "To address this, we investigated the role of IL-1β in mediating RCC tumor cell invasion as a measure of tumor progression." (PMID 23342250, 2012). "At day 43, mice carrying cells secreting relatively low levels of IL-1β (1/16 B16F10-IL-1β) harboured significantly smaller tumours (277 mm2) than those of B16F10-vector cells (376 mm2)." (PMID 23065753, 2012).
tumor (continued). "Here, we report that inflammasome proteins overexpressed in tumour cells play a key role in local tumour control, by responding to stimulation from DAMPs, PAMPs and therapeutic treatment, resulting in IL-1β secretion and neutrophil recruitment." (PMID 23065753, 2012). "Studies in mouse models have demonstrated that inhibition of IL-1β signaling, although IL-1 receptor antagonists or knockout of the IL-1β gene, reduced tumor blood vessel formation." (PMID 23342250, 2012). "This suggested that the tumour-derived IL-1β induced neutrophil infiltration through the activation of IL-1β receptor signalling in host cells." (PMID 23065753, 2012). "Paradoxically, when tumour-derived IL-1β reaches a certain threshold, it can also limit tumour growth in vivo." (PMID 23065753, 2012). "Lung tumor cells over-expressing IL-1β enhanced macrophage recruitment and tumor angiogenesis when implanted into syngeneic mice." (PMID 21699731, 2011). "Proinflammatory cytokines such as IL-1β create a milieu in the tumor that is supportive for the activation of T- effector cells." (PMID 21779410, 2011). "Together, these findings indicate that there was high incidence of CCL2, CCL5, TNFα and IL-1β expression in the tumor cells in the three groups of cancer patients, and that the expression of TNFα and IL-1β was further elevated in the IDC-with-relapse group." (PMID 21486440, 2011). "Treatment of a HR tumor cell line with IL-1β induced the expression of pro-inflammatory cytokines involved in the innate immune responses, including MCP-1, GM-CSF and TNF-α." (PMID 21978632, 2011). "Tumour tissue concentrations of IL-1β protein correlated with serum CRP concentrations (r = 0.31, P = .05; linear regression) and tumours with diffuse or patchy inflammatory cellular infiltrate were associated with elevated serum CRP." (PMID 21760776, 2011). "Treatment of the HR tumor line with IL-1β induced expression of cytokines of the innate immune responses." (PMID 21978632, 2011). "To investigate this possibility, we tested the ability of TNFα and IL-1β to induce in the tumor cells properties that are typical of EMT." (PMID 21486440, 2011). "As discussed later it was also observed that the presence of IL-17-expressing T cells was due to the secretion of IL-1β and IL-23 p19 by tumor infiltrating macrophages." (PMID 21875439, 2011). "Tumor-derived factors, such as pro-inflammatory cytokines IL-6 and IL-1β, promote the formation of MDSCs resulting in their accumulation in the blood, lymphoid organs and tumor." (PMID 24212948, 2011). "CCL2, CCL5, TNFα and IL-1β were expressed at very low incidence in normal breast epithelial cells, but their incidence was significantly elevated in tumor cells of the three groups of cancer patients." (PMID 21486440, 2011). "A HR tumor cell line, SK-N-SH, was also used for detecting the response to IL-1β, a cytokines which is involved in the innate immune responses." (PMID 21978632, 2011). "We showed an increased expression of MCP-1, GM-CSF and TNF-α in the HR tumor cell line pulsed with IL-1β, both by flow cytometry and cytokine array analyses." (PMID 21978632, 2011). "Consistent with the ability of vitamin D3 to inhibit the release of IL-1β from macrophages, vitamin D3 restored the sensitivity of tumor cells to TRAIL." (PMID 20661477, 2010). "Epithelial NF-κB activation results from the rich abundance of IL1β, TNFα and TLR-agonists in the tumour microenvironment, and IL1β, TNFα and many other cytokines and chemokines (i.e. IL6, CXCL2, CCL2 and CCL20) are transcriptional targets for NF-κB." (PMID 20478049, 2010). "Antigen-presenting cells migrate into and out of tumour tissue to present tumour antigen to T-helper cells, as well as to produce cytokines, such as interleukin-1 beta and TNF-alpha that stimulate T-helper cells." (PMID 21461373, 2010). "The HNSCC is a Th17-promoting milieu because of the release of IL-23 and -6 by the tumour cells itself and by TILs and IL-1β by tumour-infiltrating immune cells." (PMID 20877351, 2010).
tumor (continued). "Because S100A8 is the downstream target of IL1B, our results strongly support the potential involvement of IL1B in tumor progression." (PMID 20096140, 2010). "For animals treated with mcr84 or GU81, we found that decreases in serum levels of IL-1β and IL-6 were highly correlative with changes in tumor size in the presence of anti-VEGF therapy." (PMID 19888452, 2009). "Though VEGF is the primary stimulant for tumor angiogenesis, IL-1β can also stimulate in vitro endothelial cell migration and proliferation and angiogenesis in mouse models of cancer via up regulation of VEGFR2." (PMID 19888452, 2009). "Although activation of oncogenes has been shown to induce expression of IL-1β in tumour cells, we were unable to detect secreted IL-1β in the media of HC-11/R1 cells following iFGFR1 activation (data not shown)." (PMID 19393083, 2009). "We therefore have evaluated the effect of IL-6 modulators, i.e. IL-1β, prostaglandin E2, 17β-estradiol, and 1,25-dihydroxyvitamin D3, on expression and synthesis of the cytokine at different stages of tumour progression." (PMID 18205904, 2008). "Most of the cytokines that were preferentially present in ER-negative tumours (IL-1β, IL-6, IL-8, IL-10, IL-12, MCP-1 and MIP-1β) were also more abundant in high-grade tumours." (PMID 17261184, 2007). "On the other hand, IL-2, IL-6, IL-8, IL-10, IFN-γ, MCP-1, MIP-1β, TNF-α and, to a lesser extent, IL-1β and IL-13 were significantly overexpressed in ER-negative tumours compared with ER-positive ones, with the greatest differences observed for IL-8 and MCP-1." (PMID 17261184, 2007). "Human cancer xenografts in mice receiving systemic IL-1ra administration showed decreased tumor growth and metastases only when the tumor secreted significant concentrations of IL-1β." (PMID 17096856, 2006). "Subsequently, by the (local) release of IL-1β the endothelial cells stimulate the expression of at least three major cellular adhesion molecules on their own cell membrane to which circulating tumour cells now easily can adhere and next form a metastasis." (PMID 17088916, 2006). "Tumour chronic inflammatory infiltrate and tumour tissue IL-1β overexpression are potential independent factors influencing systemic inflammation in oesophagogastric cancer patients." (PMID 17088911, 2006). "Results of IL-1α or IL-1β mRNA expression in several tumor cell lines evaluated by quantitative RT-PCR." (PMID 17096856, 2006). "In the present study, median IL-1β concentrations were 10–100-fold higher than IL-6 in the tumour tissue and there was a weak but significant correlation between tumour tissue IL-1β concentration and serum CRP." (PMID 17088911, 2006). "Lower ratios of IL-1ra:IL-1β within the tumor correlated with increased concentrations of VEGF protein." (PMID 17096856, 2006). "This functional impairment of Tregs was further linked to an enhanced TH17 cell response, marked by increased secretion of IL‐1β, which aligns with the study's hypothesis that reducing Treg‐mediated suppression could invigorate anti‐tumor immunity." (PMID 41560416, 2026). "As shown, M1 macrophage markers-including IL-1β, IL-6, iNOS, and TNFα-were significantly increased in THP-1 cells co-cultured with N4BP1-deficient TSCC cells compared to those co-cultured with control tumor cells." (PMID 41513619, 2026). "The Gal-9/TIM-3 pathway partially activates cytokine production IL-6, IL-8, and IL-10, but not IL-1β, IL-12p70, or TNFα in response to LPS in gastric cancer tissue-derived tumor-associated macrophages, TAMs." (PMID 41596489, 2026). "However, persistent IL-1β signaling augments tumor invasiveness and intravasation and contributes to the formation of pre-metastatic niches by mobilizing bone marrow–derived cells and promoting extracellular matrix remodeling." (PMID 41596738, 2026).